PKD1 (polycystin 1, transient receptor potential channel interacting)
Diseases named in the same sentence as PKD1 in open-access papers (continued):
Sharing a sentence is not in itself a finding about the gene and the disease.
cancer (63 papers, 2009 to 2026). A tumor composed of atypical neoplastic, often pleomorphic cells that invade other tissues. "Gpnmb (osteoactivin), a protein under Tfeb regulation normally associated with cancer metastasis and neuroinflammation, was also increased in Pkd1 KO MEFs." (PMID 36794754, 2023). "PKD1 was found down-regulated in invasive breast, advanced prostate and gastric cancers with low expression associated with cancer aggressiveness and metastasis, thus suggesting that this kinase serves as a tumor suppressor." (PMID 35805075, 2022). "In fact, it has become increasingly clear that PKD2 and PKD3, opposite to PKD1, associate with more malignant cancer phenotypes and promote tumorigenesis and progression." (PMID 33807058, 2021). "In multiple cancer cell lines, overexpression of constitutively-active or wild type alleles of PKD1 leads to a significant reduction in directed cell migration while an increase in cell migration is observed when PKD1 is knocked down." (PMID 26848698, 2016). "We identified and experimentally confirmed three striking examples of cancer mutations directly leading to a catalytic specificity drift, PKD1 D665N, PKCγ D484N, and M501I." (PMID 26388441, 2015). "It is possible that loss of PKD1 expression and the resulting change in the expression of MMPs is part of the switch driving the progression from a benign to an invasive, malignant tumour." (PMID 19243594, 2009). "Since ADPKD and cancer present several common molecular features, several authors proposed that mutations in PKD1 or PKD2 might be relevant in predisposing patients to kidney cancer." (PMID 37510333, 2023). "In addition to the regulation of a variety of cancer-associated biological processes, PKD1 signaling actually promotes CSC maintenance in some cancers." (PMID 36497140, 2022). "Although the phosphorylation of Snail mostly promotes EMT through E-cadherin suppressive activity, PKD1-mediated phosphorylation of Snail at S11 suppressed EMT and reduced its transcriptional repressive activity, which is associated with the epigenetic suppression of PKD1 in several cancers." (PMID 31275381, 2019). "The dysregulation of PKD1, a serine-threonine kinase, has been associated with cancer progression." (PMID 22523587, 2012). "In addition, studies suggest that LPA/PKD-1 signaling may be associated with the stemness of cancer cells." (PMID 34168243, 2021). "This could be explained by polyclonality of the cysts or a growth advantage in cell culture of cells with a single germline mutation over cells that were PKD1 null, as were reported for other systems, were cancer cells, or were outgrown by wild‐type cells in standard culture conditions." (PMID 32163234, 2020). "PC1 functional modulation was performed in xenograft models using an extracellular mechanosensitivity-blocking antibody, and in cancer cell lines via polycystic kidney disease 1 (PKD1) siRNA." (PMID 42003915, 2026). "Previous studies have shown that PKD1 can regulate various biological processes, including cell proliferation, survival, motility, and so on, and ultimately alter cancer cell behaviors." (PMID 35337339, 2022). "Another mechanism through which PKD1 suppresses cancer aggressiveness consists of the inhibition of EMT." (PMID 35805075, 2022). "The results indicated that PKD1 was highly expressed in cancer tissue, grade 3, positive lymph node metastasis, positive peritoneal cytology, and recurrence groups." (PMID 35816294, 2022). "During the transgenic model induced by KRAS12D, the expression of PKD1 contributes to the formation of precancerous lesions, indicating that PKD1 plays an essential role in the origination and progression of cancer cells." (PMID 35816294, 2022). "Although it is known that PKD1 affects cell growth, proliferation, and migration, the results were observed differently depending on cancer cell lines." (PMID 34064452, 2021).
cancer (continued). "This means that PKD1 improves cell viability by making tissues resistant to changes in the surrounding environment for cancer growth." (PMID 34064452, 2021). "Although most studies support a pro-proliferative role of PKD in various biological systems, some have shown an opposite antiproliferative function of PKD1 in several cancers, including prostate, lung, and colon cancer." (PMID 33807058, 2021). "Pkd1 is a tumor suppressor gene that plays a crucial role in many different types of cancers including BC." (PMID 33947955, 2021). "The molecular relationship and the function between PKD1 and cancer is well known, such as increased or decreased cell proliferation and promoting or suppressing cell migration depending on the cancer cell type specifically." (PMID 34064452, 2021). "The protein kinase D (PKD) family has emerged as a promising target for cancer therapy with PKD1 being most intensively studied; however, its role in HNSCC has not been investigated." (PMID 30419840, 2018). "Although this serine/threonine kinase is a major cellular target for the tumor-promoting phorbol esters and growth factors which rapidly induce its activity, PKD1 has a complex relationship with respect to cancer development." (PMID 28056869, 2017). "An equally efficient strategy in cancers that underwent a switch from expression of PKD1 to the oncogenic versions PKD2/3 is the use of pan-PKD inhibitors like CRT0066101." (PMID 26848698, 2016). "The ability of PKD1 to decrease tumor hypoxia and enhance tumor vasculature suggest that PKD1 can improve delivery of cancer drug(s) in tumors." (PMID 25149539, 2014). "Active PKD1 regulates cancer related signalling pathways such as mitogen-activated ERK kinase/extracellular signal-regulated kinase (MEK/ERK), nuclear factor-kappa B (NFκB) and histone deacetylase (HDAC) pathways." (PMID 25287328, 2014). "The suppression of PKD1 expression coincided with the distinct change in the β-catenin localization in cancer tissues." (PMID 25149539, 2014). "Our studies are in accordance with other studies which also suggest the role of PKD1 in suppression of cellular motility of cancer cells." (PMID 25149539, 2014). "In conclusion, our study elucidates a new molecular paradigm involving PKD1 signaling in mediating the anti-cancer effects of curcumin." (PMID 22523587, 2012). "PKD1 suppresses cancer cell epithelial to mesenchymal transition by inhibitory phosphorylation of transcription factor Snail, a known E-cadherin repressor." (PMID 22511927, 2012). "In human cancer cell lines, PKD1 can be phosphorylated at multiple sites including Y463, S910 (corresponding to murine Y469, S916)." (PMID 21696630, 2011). "Interestingly, tumor cells in cancer nests showed low to moderate levels of PKD1 expression, along with low levels of CD44 expression." (PMID 36497140, 2022). "PKD1 regulates the glycolytic metabolism of cancer cells in hypoxia conditions." (PMID 35805075, 2022). "This PKD1 signaling-mediated CSC phenotype might uniquely contribute to the secondary colonization of metastatic cancer cells in other organs, such as the liver." (PMID 36497140, 2022). "Therefore, PKD1 down-regulation contributes to cancer development and progression by stimulating the Wnt/β-catenin signaling cascade." (PMID 35805075, 2022). "Intriguingly, PKD-1+ cancer cells presented a distinct distribution between different patients." (PMID 34168243, 2021). "As p68 has been reported to participate in cancer development and progression by functioning in several key cellular activities of cancer cells, such as cancer cell proliferation 24, 25, we examined p68-regulated cell proliferation in Pkd1 mutant renal epithelial cells." (PMID 32724471, 2020). "As PKD1 contributes to BPA-induced MCF-7 cells proliferation in vitro, we explored whether PKD1 may sensitize cancer cells to BPA in vivo." (PMID 32082170, 2019).
cancer (continued). "PKD1 is involved in numerous biological functions, such as cell proliferation, differentiation, apoptosis, invasion, and motility (reviewed in and plays a crucial role in cancer." (PMID 32082170, 2019). "The study also sought to investigate the functional implication of PKD1 in HNSCC by systematically determining its cancer-associated biological properties in HNSCC cells in vitro and in vivo and to assess the potential value of targeting PKD1 for cancer therapy." (PMID 30419840, 2018). "Interestingly, both tumor suppressive and tumor promoting functions of PKD1 have been reported, which couples to its up- or down-regulation in these tumors, implying a tumor type-specific function of PKD1 in cancer." (PMID 30419840, 2018). "In this context, while specific inhibition of PKD1 could provide clear therapeutic advantages in cancer, our results indicate that this type of treatments could represent a high risk for associated neurodegeneration." (PMID 29273751, 2017). "Inhibition of PKD1 can lead to pathological conditions such as cancer." (PMID 27456846, 2016). "PKD1 has a complex relationship with respect to cancer development." (PMID 25287328, 2014). "Thus, the deregulation of PKD1 affects multiple signaling pathways, resulting in chronic diseases like cancer." (PMID 22523587, 2012). "In addition, although PKD1 can maintain an epithelial phenotype, via negatively regulating significant molecules that regulate EMTs in some cancer cells, this study demonstrates that PKD1 signaling in pNETs is required for concomitant expression of vimentin and E-cadherin in CSCs." (PMID 36497140, 2022). "As CD36 expression in cancer cells drives stem cell-like traits, and promotes drug resistance and metastatic potential of CSCs, PKD1-mediated CD36 expression might also play an important role in metastatic progression of pNETs, very likely via CD36-mediated fatty acid metabolism." (PMID 36497140, 2022). "The seemingly opposing effects of PKD1 on cell proliferation in different cancer cells are both interesting and intriguing, suggesting that other unknown factors or the cellular environment may alter the behaviors of PKD1 in cancer cells." (PMID 33807058, 2021). "Dysregulated PKD1 expression could result in the pathogenesis of some cancers." (PMID 30619291, 2018). "Therefore, targeting PKD1 or PKD1 downstream signaling may be efficient to drive ROS to levels where they are toxic for cancer cells." (PMID 28361035, 2017). "Therefore, it is likely that PKD1 not only affects the ability of cancer cells to escape from the primary tumor and invades through the surrounding matrix and enter the bloodstream but also may impact their ability to adapt to their new environment." (PMID 23971832, 2013). "Emerging evidence suggests that cancer stem-like cell populations, characterized by markers such as CD44 and Protein kinase D1 (PKD1), contribute to intratumoral heterogeneity and tumor maintenance in PanNETs." (PMID 40648806, 2025). "PKD1 not only controls dynamic actin turnover and cell migration, but is also involved in maintaining epithelial phenotype and preventing EMT in various cancer cells." (PMID 37293129, 2023). "We emphasize that early targeted genetic testing is a priority if TSC2/PKD1-CGS is suspected; extended MLPA or NGS is necessary for affected children with early onset or recurrent malignant tumors." (PMID 36979978, 2023). "Some prior studies of PKD1 have documented a role of overexpressed PKD1 in activating of some of these signaling pathways in CRC and other cancer cells." (PMID 37542051, 2023). "It is warranted for deep mechanistic investigation as to how PKD1 signaling is involved in the ATX–LPA axis in the regulation of unique plastic CSC subsets with partial EMT in pNETs and other types of cancer with robust angiogenesis." (PMID 36497140, 2022).
cancer (continued). "Therefore, identification of the PKD1 pathway in CSC plasticity with a partial EMT phenotype may provide new insights into CSC biology in a variety of cancer types, since EMT is important during the metastatic stage, while E-cadherin-induced MET facilitates subsequent colonization." (PMID 36497140, 2022). "PKD1 also activates PI3K/Akt signaling and regulates Notch 1 signaling in several different types of cells, such as cancer cells and vascular endothelial cells." (PMID 36497140, 2022). "The PKD family contains three isoforms, including PKD1, 2 and 3, which can be activated by lysophosphatidic acid (LPA), a lipid signaling mediator that can promote stem cell-like features in cancer cells and malignant progression." (PMID 36497140, 2022). "ER+ BC cells grown in coculture with DLL4+-HMVECs had higher levels of gene expression of cancer stemness-related genes (CD44, ALDH1A1, KLF4, and CD36) and PKD-1, as compared to ER+ BC cells grown in monoculture." (PMID 34168243, 2021). "Overall, in contrast to the negative regulation of EMT, migration, and invasion by PKD1, PKD2 and PKD3 generally promote tumor metastasis by stimulating EMT and tumor cell migration/invasion in many cancer types." (PMID 33807058, 2021). "During cancer cell migration, SSH1 is identified as a substrate for PKD1-regulation of cofilin activation." (PMID 33123308, 2020). "A recent study demonstrated PTPN13 involvement in cisplatin sensitivity of HNSCC cell lines (WSU-HN6 and CAL-27) where cancer-derived IgG inhibition upregulates PTPN13, resulting in the inhibition of the SRC/PKD1/AKT pathway." (PMID 33322542, 2020). "There were discrepancies between Pkd1 mRNA levels and PC1 protein levels in some cancer cell lines, as well as discrepancies between Pkd2 mRNA levels and PC2 protein levels." (PMID 31251475, 2019). "PKD1, the most extensively studied PKD isoform, has been shown to be dysregulated in a number of cancer types and plays important roles in tumor cell biology." (PMID 30419840, 2018). "Moderate level of PKD1 expression was detected in almost all the cancer cell lines (SW480, SW48, T-84 and LoVo), except the HT-29 cell line, which showed very little PKD1 expression." (PMID 25149539, 2014). "Emerging evidence has demonstrated the involvement of PKD1 and PKD2 in several cancer hallmarks, including proliferation, apoptosis, and interaction with the tumor micro-environment, thus suggesting the potential contribution of this family of proteins to tumorigenic processes." (PMID 37510333, 2023). "Unexpectedly, PKD1 was found to be not helpful for cell proliferation in stem cells, unlike in cancer cells." (PMID 34064452, 2021). "Most recently, some papers have been published on the correlation between PKD1 and PKD2 and cancer." (PMID 34064452, 2021). "First, patients with TSC2/PKD1 CGS have high mutation burden and produce several neoantigens, which are produced by cancer cells that have not been previously recognized by the immune system." (PMID 31870441, 2019). "Interestingly, ASNS expression was further increased in Pkd1−/− MEFs upon glucose deprivation both at the mRNA and protein level, in line with the idea that ASNS mediates the glutamine compensatory utilization and with previous evidence in cancer." (PMID 38684863, 2024). "In oral squamous cell carcinoma cells, hypoxia induces the expression and activation of PKD1, which, in turn, activates the p38 MAPK signaling cascade, thus stimulating the expression and activation of HIF-1α and, consequently, the metabolic switch of cancer cells." (PMID 35805075, 2022). "Targeting the LPA/PKD-1 signaling pathway may function as a double-edged sword against both vascular and CSC compartments to alleviate therapeutic resistance while also controlling cancer relapse and metastasis." (PMID 34168243, 2021).
cancer (continued). "In summary, depending on the tumor type, PTPN13 may regulate resistance to anti-cancer therapies through its anti-apoptotic role via the FAS pathway, or through regulation of secondary EGFR pathways (ephrinB1/ErbB and SRC/PKD1/AKT), or through an indirect action on microtubules mediated by ephrinB1." (PMID 33322542, 2020). "Furthermore, PKD1 is known to be involved in inhibiting invasion, metastasis and epithelial-mesenchymal transition (EMT) of cancer cells by regulating the expression of matrix metalloproteinases (MMPs) and the functions of snail transcription factor, respectively." (PMID 22523587, 2012).